LARP4 (La ribonucleoprotein 4)
Description:
RNA binding protein that binds to the poly-A tract of mRNA molecules. Associates with the 40S ribosomal subunit and with polysomes. Plays a role in the regulation of mRNA translation. Essential for proper regulation of cell morphology and cytoskeletal organization.
Synonyms: PP13296
Tractability: PROTAC: ubiquitination databases record sites on it; its protein half-life has been measured.
Gene: Protein-coding gene on chromosome 12 (50,392,383 to 50,480,007, forward strand). Ensembl gene ENSG00000161813.
Subcellular location: Cytoplasm, Stress granule; Cytoplasm, cytosol
Subcellular location (Human Protein Atlas): Cytosol; Nucleoli fibrillar center
Gene Ontology:
Molecular function: mRNA 3'-UTR binding; poly(A) binding; protein binding; RNA binding; nucleic acid binding
Biological process: positive regulation of translation; post-transcriptional regulation of gene expression
Cellular component: cytoplasmic stress granule; cytosol; cytosolic small ribosomal subunit; membrane
Genetic constraint (gnomAD): Loss-of-function variants: 10 observed, 45.62 expected, observed/expected ratio (o/e) 0.22, 90% interval 0.13 to 0.37. The upper end of that interval is the gene's LOEUF score, 0.37, which puts it in group 1 of 6, group 1 being the genes least tolerant of losing a copy. Missense variants: 486 observed, 556.7 expected, observed/expected ratio (o/e) 0.87, 90% interval 0.81 to 0.94. Synonymous variants: 173 observed, 192.88 expected, observed/expected ratio (o/e) 0.9, 90% interval 0.79 to 1.02.
Homologues: Orthologues: chimpanzee LARP4 (99% identical), macaque LARP4 (97% identical), dog LARP4 (90% identical), pig LARP4 (86% identical), rat Larp4 (85% identical), mouse Larp4 (84% identical), guinea pig LARP4 (82% identical), tropical clawed frog larp4 (61% identical), zebrafish larp4aa (51% identical), zebrafish larp4ab (48% identical), Drosophila melanogaster Larp4B (32% identical), Caenorhabditis elegans larp-5 (22% identical). Paralogues in human: LARP4B (37% identical), LARP1 (17% identical), LARP1B (17% identical), LARP7 (11% identical), LARP6 (10% identical), SSB (8% identical).
Diseases named in the same sentence as LARP4 in open-access papers:
LARP4 is named in the same sentence as 14 diseases in open-access papers, as found by Europe PMC text mining. Sharing a sentence is not in itself a finding about the gene and the disease. The quoted sentences say what the papers report.
gastric cancer (6 papers, 2018 to 2022). A primary or metastatic malignant neoplasm involving the stomach. "La ribonucleoprotein 4 (LARP4) acts as a molecular sponge of miR-424 in gastric cancer, in which a similar ceRNA related mechanism was reported." (PMID 33168027, 2020). "The upregulation of circ-PVT1 and downregulation of circ-LARP4 in gastric cancer are independent prognostic factors, and circ-PVT1 overexpression predicts better OS and DFS." (PMID 30064463, 2018). "For example, circRNA LARP4 is lowly expressed in gastric cancer tissue, and its expression level is significantly correlated with the pathological stage and overall survival rate of gastric cancer patients." (PMID 36465346, 2022). "Both circ-LPHN2 and circ-LARP4 are lowly expressed in gastric cancer tissues." (PMID 30064463, 2018). "For example, circular RNA_LARP4 expression positively correlates with the tumor suppressor LATS1, the direct target of miR-424-5p in gastric cancer." (PMID 30458784, 2018).
breast carcinoma (5 papers, 2016 to 2023). "Importantly, LARP4 has also been implicated as a negative regulator of cancer cell migration and invasion in prostate and breast cancers, a process that is more directly relevant to what is known of PKA function." (PMID 30274258, 2018). "In a recent study by Zhang and colleagues, the expression level of circular RNA La‐related RNA‐binding protein 4 (circ‐LARP4) and its impact on tumor characteristics, prognosis, and treatment of breast cancer were evaluated in clinical tissue samples and cell culture." (PMID 34545638, 2021). "They showed a significant decline in circ‐LARP4 level in breast cancer tissues." (PMID 34545638, 2021). "We demonstrate that LARP4 depletion induces cell elongation and increases cell migration speed in both PC3 prostate cancer cells and MDA‐MB‐231 breast cancer cells." (PMID 27615744, 2016). "Here we show that LARP4 depletion induces cell elongation in PC3 cells and MDA‐MB‐231 breast cancer cells." (PMID 27615744, 2016).
ovarian carcinoma (5 papers, 2020 to 2023). A malignant neoplasm originating from the surface ovarian epithelium. "Furthermore, circ_LARP4 suppresses cell proliferation and migration in ovarian cancer by upregulation of LARP4 by competitive binding to miR-513b-5p." (PMID 34858987, 2021). "LARP4 also functions as a suppressor for motility of ovarian cancer cells." (PMID 34738869, 2021). "Furthermore, a recent study reported that the LARP4 mRNA-high expression group showed longer overall survival compared with the LARP4 mRNA-low expression group, implying a positive correlation of LARP4 mRNA levels in ovarian cancer tissues with patient prognosis." (PMID 37169020, 2023). "Therefore, LARP4 could suppress motility and metastatic potential of ovarian cancer cells." (PMID 37169020, 2023).
prostate carcinoma (4 papers, 2016 to 2023). A carcinoma that arises from epithelial cells of the prostate gland. "KD of LARP4 induces elongated phenotype in the prostate cancer cells and increased cell migration, while overexpression of LARP4 decreased the elongation." (PMID 37169020, 2023). "Depletion of LARP4 in PC3 prostate cancer cells resulted in cell elongation, a phenotype similar to that of depleting several other proteins including the Rho GTPases RhoA, RhoU and the formin Dia1." (PMID 27615744, 2016). "We previously identified LARP4 in an RNAi screen as one of several genes that regulate the shape of PC3 prostate cancer cells." (PMID 27615744, 2016). "The only RBP that was identified to be associated with advancement of prostate cancer based on all three nonphosphoproteomic datasets was LARP4 (La ribonucleoprotein 4)." (PMID 37591798, 2023). "Interestingly, LARP4 has previously been shown to regulate migration, invasion, and shape of prostate cancer cells, validating our analysis approach for identifying functionally meaningful RBPs." (PMID 37591798, 2023). "LARP4 is known to stabilize mRNA through binding to their poly-A tract but has also been identified as a negative regulator of cell migration and invasion in a prostate cancer cell line." (PMID 30274258, 2018).
osteosarcoma (3 papers, 2021). A usually aggressive malignant bone-forming mesenchymal neoplasm, predominantly affecting adolescents and young adults. "Hu et al100 showed that circ‐LARP4 level was decreased in osteosarcoma tissues compared to non‐tumour samples and circ‐LARP4 was associated with Enneking stage." (PMID 33103338, 2021). "In osteosarcoma cell lines with overexpressed circRNA LARP4, the IC50 value related to cisplatin and adriamycin was significantly lowered." (PMID 34566636, 2021). "Circ-LARP4 is downregulated and correlated with prolonged survival in osteosarcoma, due to its ability to increase tumor cell sensitivity to doxorubicin by sponging miR-424." (PMID 34852843, 2021). "Their data suggested that high expression of circ‐LARP4 was associated with prolonged survival profiles and decreased Enneking stage and overexpression of circ‐LARP4 enhanced chemosensitivity to doxorubicin and cisplatin through sponging miR‐424 in development of osteosarcoma." (PMID 33103338, 2021). "They found that circRNA LARP4 was negatively correlated with the Enneking staging of osteosarcoma." (PMID 34566636, 2021).
schizophrenia (2 papers, 2023 to 2024). A major psychotic disorder characterized by abnormalities in the perception or expression of reality. "Among the six candidate genes, four (BDH2, CLDND1, GAS8, and TRIP4) displayed DTU events in all schizophrenia samples, while the other two genes (LARP4 and NVL) showed significant DTU events in specific subgroups." (PMID 38508189, 2024). "LARP4 has been found to show differential expression between the unaffected siblings and first-degree relatives of schizophrenia patients compared with unaffected individuals unrelated to the patients." (PMID 38508189, 2024). "LARP4 has been found to show differential expression between the unaffected siblings and first-degree relatives of schizophrenia patients compared to unaffected individuals unrelated to the patients." (PMID 37503064, 2023). "Amongst the six candidate genes, four (BDH2, CLDND1, GAS8, TRIP4) displayed DTU events in all schizophrenia samples, while the other two genes (LARP4, NVL) showed significant DTU events in specific subgroups." (PMID 37503064, 2023).
epilepsy (1 paper, 2015). A brain disorder characterized by episodes of abnormally increased neuronal discharge resulting in transient episodes of sensory or motor neurological dysfunction, or psychic dysfunction. "The high-hubs in community C are either involved in mechanisms related to epilepsy pathogenesis (DFF40 and PTPRZ1) or in the control of gene expression and translation initiation (LARP4, EIF1)." (PMID 26011637, 2015).
cancer (12 papers, 2016 to 2024). A tumor composed of atypical neoplastic, often pleomorphic cells that invade other tissues. "Five cancer‐associated missense mutations and one nonsense mutation (a protein‐truncating stop codon) were introduced into LARP4, several of which enhanced the phenotype induced by LARP4 overexpression." (PMID 27615744, 2016). "Introduction of some of these cancer‐associated mutations, including a truncation mutant, into LARP4 enhances its effects on cell morphology." (PMID 27615744, 2016). "The catalogue of somatic mutations in cancer (COSMIC) reports more than 130 LARP4 mutations in various cancer types." (PMID 27615744, 2016). "We propose that LARP4 inhibits migration and invasion of cancer cells, and that some cancer‐associated mutations stimulate these effects of LARP4." (PMID 27615744, 2016). "Over 130 LARP4 mutations in cancers are reported in the COSMIC." (PMID 27615744, 2016). "Analyzing the upregulated genes, LARP4 upregulation was the only upregulated gene that was detrimental to cancer as its upregulation can inhibit migration and invasion." (PMID 35342659, 2022). "In respect to antitumor role of LARP4, low expression of this circRNA is correlated with poor prognosis of patients with cancer." (PMID 32756305, 2020). "Recent studies have shown that LARP4 as a La-related RNA-binding protein inhibits cancer cell migration and invasion." (PMID 28893265, 2017). "In either case, our results with LARP4 are consistent with a growing body of evidence indicating a prominent role for RBPs in both the development and progression of cancer [Wurth and Gebauer, 2015]." (PMID 27615744, 2016). "We also found that LARP4 suppresses migration, as the migration speed of two cancer cell lines that migrate predominantly as single cells, PC3 and MDA‐MB‐231, increased upon LARP4 depletion." (PMID 27615744, 2016). "The exact mechanism of action of LARP4 in altering cancer cell morphology, migration and invasion is yet to be determined." (PMID 27615744, 2016). "In addition, some reported factors, including E2F5, PTEN/AKT/mTOR signaling, DUSP11, PRPF39, and LARP4, are involved in miR-513b-5p regulated cancer progression." (PMID 34120890, 2021). "Therefore, enhancing expression of circRNA LARP4 can provide condition for a decrease in viability of cancer cells." (PMID 32756305, 2020). "In this study, we show that LARP4 affects cancer cell morphology, migration and invasion." (PMID 27615744, 2016). "In addition to the effect of LARP4 on cancer cells in 2D, LARP4 depletion resulted in cell elongation in 3D Matrigel and increased invasion." (PMID 27615744, 2016). "Furthermore, recent studies reveal that LARP4 regulates migration and invasion of cancer cells." (PMID 37169020, 2023). "LARP4 and LARP4B exhibit similar overall architectures but with different functionalities in cancer and other processes, verified by direct comparisons." (PMID 39554137, 2024). "We therefore conclude that LARP4 alters shape, migration and invasion of PC3 and MDA‐MB‐231 cancer cells." (PMID 27615744, 2016). "Elucidating how LARP4 may increase mRNA stability within the colon, as well as which targets may be most affected LARP4 overexpression may provide further insight into its potential role in CRC, particularly given the important role for mRNA stabilization in the shaping of the cancer transcriptome." (PMID 34548904, 2021).
tumor (8 papers, 2016 to 2023). "Downregulated circ-LARP4 at the tumor site of BC was related to increased tumor size, advanced clinical stage, and bad prognosis in BC." (PMID 36926585, 2023). "Conversely, circ-ITCH, circ-ITCH, circ-0007874 and circ-LARP4 were served as tumor suppressor in OC, which inhibited OC cells growth by acting as competing endogenous RNAs to sponge miRNAs." (PMID 35687899, 2022). "We further characterized a circLARP4 derived from LARP4 gene and demonstrated that circLARP4 was a tumor suppressive factor in GC by sponging miR-424 and regulating LATS1 expression." (PMID 28893265, 2017).
infection (2 papers, 2023 to 2024). The state of being infected such as from the introduction of a foreign agent such as serum, vaccine, antigenic substance or organism. "Similar to HNRNPM, RAI, LSM14A, LARP4, and CNOT2 showed complete loss of full-length protein during the course of infection." (PMID 38953667, 2024). "Most candidate proteins such as PLA2G4A, FASN, HNRNPH2, and LARP4 showed detectable cleavage products at 5 h.p.i. that were stable at later times of infection." (PMID 38953667, 2024). "As D10 is an intermediate protein that is not expressed in vΔA23-infected cells, it is possible that the failure to promptly degrade host cell mRNAs in vΔA23 infection prevents the recruitment of LARP4 to viral factories." (PMID 37594266, 2023). "The endogenous LARP4 enrichment in viral factories was detected as early as 4 h post-infection (hpi)." (PMID 37594266, 2023).
LARP4 also shares sentences with these, for which no sentence is quoted: bladder cancer (1 paper); cerebral malaria (1); hepatocellular carcinoma (1); leukemia (1).